GPRC5D (G protein-coupled receptor class C group 5 member D)
Diseases named in the same sentence as GPRC5D in open-access papers (continued):
Sharing a sentence is not in itself a finding about the gene and the disease.
myeloma (continued). "G protein-coupled receptor C5 family member D (GPRC5D) is highly expressed on the surface of primary multiple myeloma cells and is independent of BCMA expression." (PMID 40547010, 2025). "For multiple myeloma patients who are BCMA-negative or have low BCMA expression, as well as those who experience BCMA-negative relapse due to target cell antigen immune escape after BCMA-targeted therapy, targeting GPRC5D offers a new therapeutic direction." (PMID 40547010, 2025). "G protein‐coupled receptor family C, group 5, member D (GPRC5D), a member of the G protein‐coupled receptor (GPCR) family, has recently emerged as a promising target for immunotherapy in hematologic malignancies, particularly multiple myeloma." (PMID 40914945, 2025). "For example, SIM0500, an IgG4-based TsAb targeting BCMA/GPRC5D/CD3, has demonstrated potent T-cell redirection and cytotoxicity against myeloma cells in preclinical models, including enhanced T-cell expansion, cytokine production, and lysis of tumor cells compared to bispecific formats." (PMID 40508128, 2025). "GPRC5D is highly expressed in malignant bone marrow plasma cells derived from CD138 + MM patients, while its expression independently of BCMA, making it a potential excellent target for multiple myeloma therapy." (PMID 38783333, 2024). "Importantly, GPRC5D is expressed independently of BCMA, making it a promising target for multiple myeloma therapy." (PMID 38961036, 2024). "For example, CAR T-cell therapy for multiple myeloma targeting B-cell maturation antigen (BCMA) can be improved by simultaneous targeting of an additional antigen, e.g., G protein-coupled receptor class-C group-5 member-D (GPRC5D), to prevent BCMA escape-mediated relapse." (PMID 37087493, 2023). "One of them is G protein-coupled receptor, class C group 5 member D (GPRC5D), that due to the very promising data from the use of chimeric antigen receptor T-cells (CAR-T) and bispecific antibodies (BsAb) seems to be the ideal candidate in the relay of myeloma treatment at relapse." (PMID 37924369, 2023). "GPRC5D is independent of BCMA expression patterns on myeloma cells, and it appears to be the ideal candidate in the relay of myeloma treatment at relapse after anti-BCMA therapies." (PMID 41228264, 2025). "In multiple myeloma, some of the BsAb constructs target BCMA (teclistamab, erlanatamab), whereas others target non-BCMA epitopes on plasma cells such as GPRC5D (talquetamab)." (PMID 39861922, 2025).
multiple myeloma (32 papers, 2023 to 2026). "Other targets that have been studied in MM, such as GPRC5D, FCHR5, and CS1/SLAM F7, may also be important in patients with AL amyloidosis, and novel therapies directed at these antigens may further expand the treatment armamentarium." (PMID 39007104, 2024). "Malignant PCs in MM and AL amyloidosis share several key features which are of relevance to immunotherapeutic approaches, including the surface expression of CD38, B-cell maturation antigen (BCMA), and G-protein-coupled receptor, class C group 5 member D (GPRC5D)." (PMID 38672686, 2024).
nail disorder (2 papers, 2023). A disease involving the nail. "Patients treated with GPRC5D‐targteing BsAbs often develop skin and nail disorders and loss of taste, which is likely related to GPRC5D expression in cells that produce hard keratin." (PMID 37601851, 2023). "In addition, GPRC5D-targeting BsAbs are associated with specific ‘on target/off tumor’ toxicities including rash, nail disorders, and dysgeusia." (PMID 37501530, 2023). "GPRC5D is also expressed on cells that produce keratin, which may explain the development of skin and nail disorders in patients treated with GPRC5D‐targeting BsAbs." (PMID 37601851, 2023).
dry mouth (1 paper, 2025). "The association between GPRC5D expression and oral side effects, particularly in tissues like the salivary glands, suggests a possible mechanism behind the frequent reports of dry mouth in patients undergoing GPRC5D‐targeted therapies." (PMID 41360668, 2025).
plasma cell dyscrasias (1 paper, 2025). "In addition to BCMA-directed therapies, other CAR T targets such as GPRC5D and CD229 also appear promising for plasma cell dyscrasias." (PMID 40264764, 2025).
plasmacytoma (1 paper, 2025). Plasmacytoma is a localized mass of neoplastic monoclonal plasma cells that represents approximately 5% of all plasma cell neoplasms. "Specifically, a biallelic loss of the G-protein-coupled receptor class 5 member D (GPRC5D) gene, due to local chromosomal deletion, was identified in a patient with recurrent plasmacytoma post GPRC5D-targeted CAR-T therapy." (PMID 41194129, 2025).
tumor (31 papers, 2023 to 2026). "To note, Ramantamig (simultaneously targeting BCMA, GPRC5D tumour-associated antigens along with CD3 receptor on effector T-cells) displayed enhanced anti-tumour activity against multiple myeloma in in vitro, ex vivo and in vivo settings." (PMID 41601679, 2026). "Although GPRC5D's role in these tissues remains incompletely understood, its documented presence in the oral cavity points toward a localized on‐target off‐tumor effect that may underlie these adverse reactions." (PMID 41360668, 2025). "GPRC5D expression outside the tumor tissue is restricted and mostly displayed increased expression in the stratified flat squamous epithelium, which mitigates the risk of on-target, off-tumor toxicity development." (PMID 40649828, 2025). "Thus, cerebellar dysfunction might be a characteristic off‐tumor toxicity associated with GPRC5D‐targeted therapy." (PMID 41439209, 2025). "Toxicities primarily reflected on-target, off-tumor effects related to GPRC5D expression in epithelial tissues, including dysgeusia, xerostomia, and nail changes." (PMID 41470115, 2025). "Conversely, high tumor burden, elevated T-cell exhaustion markers, and genomic alterations such as heterozygous deletions of TNFRSF17 or GPRC5D at baseline have been associated with inferior outcomes." (PMID 40508128, 2025). "On-target, off-tumor AEs related to GPRC5D were grade 1 nail disorders, grade 1/2 pruritus, and grade 2 dry skin." (PMID 38307865, 2024). "On-target, off-tumor toxicities of GPRC5D-targeting BsAbs are related to the target’s expression on cells that are able to produce hard keratin structures, such as hair follicles, and salivary glands, and include dermatologic and oral AEs." (PMID 39001399, 2024). "Since GPRC5D is highly expressed in keratinized tissues, patients experience unique off-tumor, on-target adverse events such as skin desquamation, dysgeusia, and nail changes that adversely affect their quality of life." (PMID 39450163, 2024). "Multiple other tumor targets for TCEs, including GPRC5D, FcRH5, and CD38, are being pursued preclinically and clinically." (PMID 39364307, 2024). "Previous studies found that the expression of GPRC5D protein on the tumor cells of MM patients was specific, and, as a seven-transmembrane protein, it was difficult to detach, leading to off-target effects of TCBs." (PMID 38136320, 2023). "By simultaneously binding to CD3 on T-cells and GPRC5D on MM cells, T-cells are redirected to the tumor cells resulting in the formation of an immune synapse." (PMID 37501530, 2023). "Its design also minimizes tumor escape by targeting the N-terminal region of GPRC5D." (PMID 42254134, 2026). "In addition, patients treated with talquetamab develop skin-related events, dysgeusia, and nail-related events due to GPRC5D expression in cells that produce hard keratin and are on-target, off-tumor effects of the drug." (PMID 39941892, 2025). "Despite advancements in therapies targeting established antigens, such as BCMA, CD38, SLAMF7, and GPRC5D, specific challenges persist, including antigen escape, treatment resistance, and off-tumor toxicity, highlighting the urgent need for novel therapeutic modalities." (PMID 40597436, 2025). "Due to its high expression and antigen stability, FcRH5 has been increasingly included into poly- and bi-specific CAR platforms (for instance, FcRH5+BCMA and FcRH5+GPRC5D), which is particularly promising for combating antigen escape in the case of tumor heterogeneity." (PMID 40649828, 2025). "Tumor-intrinsic mechanisms contributing to secondary resistance include biallelic deletions or mutations affecting key target antigens, such as TNFRSF17 (BCMA) and GPRC5D." (PMID 40508128, 2025). "Therefore, GPRC5D is a promising marker for detecting tumor burden and is a reliable target for targeted therapy." (PMID 40095426, 2025).
tumor (continued). "Interestingly, the “GPRC5D high, Efficacy low” sample showed a low immune score, and the “GPRC5D low, Efficacy high” sample showed a high immune score, indicating that immune cells are contributing to the anti-tumor activity induced by BsAb5003." (PMID 38429446, 2024). "The main toxicities include cytokine release syndrome, cytopenias, hypogammaglobulinemia, and infections; on-target off-tumor adverse events involving the skin, mucosa, hair, and nails may also occur with anti-GPRC5D BsAbs." (PMID 39001399, 2024). "However, because GPRC5D is also found on keratin‐producing cells, GPRC5D‐targeted CAR‐T cells may cause unique off‐tumor toxicities." (PMID 41439209, 2025). "However, anti-GPRC5D therapy is associated with on-target off-tumor AEs, deriving from the expression of GPRC5D on non-hematopoietic tissues." (PMID 39001399, 2024). "Another study reported the development of novel NK-CAR with dual targeting capacity against BCMA and GPRC5D; dual BCM5A/GPRC5D dual-targeted CAR-NK cells improved animal survival and reduced tumor relapse compared to single-targeting CAR-NK cells." (PMID 40361380, 2025). "However, the expression of GPRC5D in cells within the oral cavity could result in on‐target off‐tumor toxicities, particularly in the form of taste disturbance, a side effect that is often underreported in clinical trials and inadequately managed in clinical routine." (PMID 41360668, 2025). "The G-protein-coupled receptor, class C, group 5, member D (GPRC5D), is another promising target of MM that is expressed on almost half of CD138-positive tumor cells in the bone marrow of patients." (PMID 38892913, 2024). "G protein-coupled receptor family C group 5 member D (GPRC5D) exhibits high selective expression on MM cell surfaces, and it remains unaffected by various anti-tumor therapies, such as IMiDs, PI, and CD38 Mabs." (PMID 38627681, 2024). "GPRC5D-targeted chimeric antigen receptor (CAR)-T and CAR-NK cell therapy, as well as bispecific T cell engagers, offer remarkable anti-tumor activities." (PMID 37277826, 2023). "A key innovation lies in the design of dual- and trispecific antibodies that engage multiple tumor antigens (e.g., BCMA/GPRC5D/CD3 or BCMA/CD3/CD28), thereby mitigating antigen escape and incorporating intrinsic co-stimulatory signaling to sustain T cell activation." (PMID 41470115, 2025). "Moreover, cryopreserved GPRC5D targeting CAR-engineered NK cells retained comparable antigen-specific cytotoxicity in vitro and demonstrated the capacity to reduce tumor burden in an antigen-dependent manner in the xenograft model." (PMID 41303706, 2025). "Bispecific TCEs in clinical development in RRMM target the tumor antigens BCMA, GPRC5D, and FcRH5." (PMID 39364307, 2024). "Immunoselection of BCMA- or GPRC5D-negative or mutant clones is an important tumor-intrinsic driver of relapse post-targeted therapies." (PMID 37653344, 2023). "To examine the tumor-intrinsic factors that promote MM antigen escape, we performed combined bulk and single-cell whole-genome sequencing and copy number variation analysis of 30 patients treated with anti-BCMA and/or anti-GPRC5D CAR T/TCE therapy." (PMID 37653344, 2023). "Dysgeusia and nail toxicities likely result from on-target, off-tumor effects, as GPRC5D is expressed in filiform papillae (lacking taste receptors) and residential plasma cells in the oral cavity, as well as in the nail keratogenous zone in preclinical models." (PMID 40343678, 2025). "It is unknown whether dysgeusia is a direct on-target, off-tumor effect because GPRC5D immunoreactivity in salivary glands is limited to resident plasma cells, and while GPRC5D is also expressed on filiform papillae, they are not responsible for taste." (PMID 38307865, 2024).
tumor (continued). "Furthermore, OriCAR-017, another GPRC5D-targeted autologous CAR T-cell therapy, features the proprietary Ori signal activation domain to enhance memory immune cells' expansion efficiency, boosting the anti-tumor effectiveness and longevity of CAR T-cells in vivo." (PMID 39468695, 2024). "In murine and nonhuman primate models, CAR-T cells targeting GPRC5D showed effective anti-MM activity in vivo, including in BCMA escape models, without on-target, off-tumor toxicity." (PMID 39468695, 2024).
cancer (7 papers, 2020 to 2025). A tumor composed of atypical neoplastic, often pleomorphic cells that invade other tissues. "Although around 45% of MM cells harbored a nonsense mutation (p.Arg233Ter), a missense mutation in GPRC5D (p.Tyr257Ser) with a cancer cell fraction (CCF) of 28% represented another subclone because both mutations were mutually exclusive after phasing the reads." (PMID 37653344, 2023). "The role of GPRC5D in cancers is yet to be defined; nonetheless, selective GPRC5D expression may be valuable as a target for antibody therapy against MM." (PMID 35628495, 2022). "There are at least 11 bsAbs targeting CD19 × CD3, EGFR × MET, gp100 × CD3, CD20 × CD3, BCMA × CD3, CTLA-4 × PD-1, CD20 × CD3, and GPRC5D × CD3, which have been approved for treatment of various cancers." (PMID 38257366, 2024). "To confirm the binding affinity to GPRC5D, we performed FCM analysis using KMS-11 and KMS-26 cells as GPRC5D-negative and positive cells, respectively, in accordance with the expression data of the Cancer Dependency Map25." (PMID 38429446, 2024). "We found that AREG, E1CAM, and GPRC5D had prognostic efficacy in the Human Protein Atlas (HPA), while their mRNA expression was not significantly different between cancer and normal tissues in the TCGA-HNSC database." (PMID 37106442, 2023).
infection (5 papers, 2023 to 2026). The state of being infected such as from the introduction of a foreign agent such as serum, vaccine, antigenic substance or organism. "Targeting GPRC5D has been thought to be associated with a lower risk of infection." (PMID 39054331, 2024). "In a cohort of 29 patients receiving GPRC5D-targeting BiAbs and 200 patients receiving BCMA-targeting BiAbs, the cumulative incidence of infection in the anti-GPRC5D group was 53% compared to 73% in the anti-BCMA cohort." (PMID 39054331, 2024). "In conclusion, results from early phase trials of GPRC5D-targeting T-cell–redirecting agents have shown promising efficacy and manageable safety profiles, including lower infection rates compared with B-cell maturation antigen- and Fc receptor-like protein 5-targeting bispecific antibodies." (PMID 38307865, 2024). "The development of CAR T cell therapy targeting B cell maturation antigen (BCMA) and other epitopes such as G-protein coupled receptor family C group 5 member D (GPRC5D) has drastically improved the ability to control advanced MM, but with a consequent risk of increasing infections." (PMID 39054331, 2024). "The relatively low rates of high-grade cytopenia and severe infections, including infections leading to death, observed with these therapies and non-overlapping AE profiles with conventional MM agents may make GPRC5D-targeting bispecific antibodies versatile combination partners." (PMID 38307865, 2024).
GPRC5D also shares sentences with these, for which no sentence is quoted: hematologic malignancies (3 papers); acute myeloid leukemia (2); cardiac failure (1); COVID-19 (1); esophageal squamous cell carcinoma (1); non-Hodgkin lymphoma (1); plasma cell leukemia (1).